EGFR (epidermal growth factor receptor)
Diseases named in the same sentence as EGFR in open-access papers (continued):
Sharing a sentence is not in itself a finding about the gene and the disease.
ischemia (10 papers, 2012 to 2025). A hypoperfusion of the BLOOD through an organ or tissue caused by a PATHOLOGIC CONSTRICTION or obstruction of its BLOOD VESSELS, or an absence of BLOOD CIRCULATION. "Rescue of ischemia and/or G7 dendrimer-mediated attenuation of cardiac EGFR signaling by exogenous EGF administration would explain the improved recovery from I/R injury, though further study is needed." (PMID 39319862, 2025). "We have previously shown in cardiac ischemia/reperfusion injury that cardiac SGLT1 interacts with EGFR to activate PKC, which in turn activates Nox2 and leads to increased ROS-production." (PMID 40932483, 2025). "Indeed, we have previously shown that cardiac EGFR signaling is attenuated following ischemia, leading to impaired recovery from I/R injury, as seen in this study." (PMID 39319862, 2025). "In this study our initial goal was to determine whether the inhibition or activation of erbB2 and EGFR signaling was able to aid or exacerbate recovery of cardiac function following global ischemia in isolated hearts from normal or streptozotocin-induced diabetic rats." (PMID 22720029, 2012). "In the present study, we investigated the activation of EGFR, PI3K/AKT, and Raf/MAPK/ERK1/2 during ischemia or reperfusion of the brain using the middle cerebral artery occlusion model." (PMID 26442853, 2015). "In the present article, we performed systematic analysis of EGFR and its two signal pathways Raf/MAPK/ERK1/2 and PI3K/AKT during ischemia and reperfusion using rat MCAO model." (PMID 26442853, 2015). "During ischemia, the activity of PI3K/AKT pathway was significantly increased, as judged from the strong phosphorylation of AKT; this activation was suppressed by the inhibitors of EGFR and Zn-dependent metalloproteinase." (PMID 26442853, 2015).
ischemic stroke (10 papers, 2017 to 2025). A stroke disorder caused by obstruction of blood flow to the brain, due to thrombotic (local blood clot formation) or embolic (due to a blood clot or other material traveling from another site) event. "AsVI treatment improved the impaired both physical and neurological cognitive functions in post-ischemic stroke rats by effectively activating EGFR/MAPK signaling cascades." (PMID 36559001, 2022). "Recent research demonstrated that it was the regulatory T cells inside the brain that exerted robust neuronal protection in ischemic stroke by suppressing neurotoxic astrogliosis through producing epidermal growth factor receptor (EGFR) ligand." (PMID 33927608, 2021). "The striatal infusion of transforming growth factor alpha (TGFα), which is a ligand for EGFR/ErbB1 has exhibited a similar neuroprotection in the rat model of ischemic stroke." (PMID 29342116, 2018). "In support of the interpretation of elevated amphiregulin in human blood prior to hemorrhagic transformation of ischemic stroke, the deleterious effect of ErbB/EGFR signaling has been demonstrated when HB-EGF is excessively expressed." (PMID 29342116, 2018). "In addition, EGFR could be used as a blood-based diagnostic biomarker for ischemic stroke." (PMID 29340078, 2017). "Therefore, the EGFR/JNK1/c-Jun signalling pathway is critical to the pathological processes of ischaemic stroke." (PMID 35815278, 2022). "The lncRNA H19/EGFR/JNK1/c-Jun signalling pathway may be a key mechanism of berberine-induced neuroprotection in ischaemic stroke." (PMID 35815278, 2022). "In human ischemic stroke patients, it has been demonstrated that systemic blood samples collected prior to hemorrhagic transformation have revealed a significant increase of amphiregulin, one of the EGFR/ErgB1 ligands." (PMID 29342116, 2018). "Finally, in vitro experiments confirmed that berberine may have a good therapeutic effect on ischaemic stroke by regulating the lncRNA H19/EGFR/JNK1/c-Jun signalling pathway." (PMID 35815278, 2022). "However, in the recovery phase of ischemic stroke, exogenous t-PA may increase the axon regeneration of the cerebral cortex through the epidermal growth factor receptor (EGFR) signaling pathway." (PMID 34970121, 2021). "We confirmed that berberine has an excellent neuroprotective effect via regulation of the lncRNA H19/EGFR/JNK1/c-Jun pathway in hypoxia-induced SH-SY5Y cell injury, making it a possible drug candidate for ischaemic stroke." (PMID 35815278, 2022). "Our previous study shows that AsVI activates EGFR/MAPK signaling cascades, promotes the proliferation as well as neurogenesis of neural stem cells (NSCs) in transient cerebral ischemic brains, and improves neurological function repair in rats with post-ischemic stroke." (PMID 36559001, 2022).
latent infection (10 papers, 2017 to 2024). "Mutations in UL135 ablating these host interactions restore EGFR levels in infected cells and diminish reactivation from latent infection." (PMID 31725811, 2019). "UL138 has also been found to affect surface levels of Epidermal Growth Factor Receptor (EGFR), with increased signaling activity enhancing latent infection of CD34+ myeloid progenitor cells." (PMID 33096622, 2020). "Human cytomegalovirus (HCMV) utilizes EGFR as a co-receptor for cell entry, and specifically regulates surface expression of EGFR to promote productive or latent infections." (PMID 32547533, 2020). "The detection of miR-US5-2 during latent infection suggests that the miRNA may modulate the EGFR signaling stimulated by UL138, perhaps as a mechanism to fine-tune the responses induced by exogenous EGF." (PMID 32759334, 2020). "Furthermore, the turnover of EGFR from the cell surface into early endosomes was reported after infection of several viruses like Zika virus and influenza virus, serving as signaling mediator and key control point for viral-induced cellular changes for productive or latent infection." (PMID 37402592, 2023). "Viral induced signaling through the Epidermal Growth Factor Receptor (EGFR) and other receptors such as integrins are key control points for viral-induced cellular changes and productive and latent infection in host organ systems." (PMID 34025614, 2021).
low grade glioma (10 papers, 2018 to 2025). A grade I or grade II glioma arising from the central nervous system. "Recent investigations report an elevated occurrence of EGFR mutations, in low-grade gliomas (LGGs) reaching up to 23%." (PMID 39186767, 2024). "Kidney Renal Clear Cell Carcinoma (KIRC) and Low-Grade Glioma (LGG) show decreased survival with TNFa and JAK-STAT pathways, respectively, where specific activating mutations are much less known than for EGFR/MAPK." (PMID 29295995, 2018). "Furthermore, we identified that Caucasian CCLs in low-grade glioma (LGG) were more sensitive to irreversible tyrosine kinase inhibitors (TKI) targeting EGFR, ERBB2 or ERBB4, such as AST-1306 (Cohen’s d = 1.71, adj." (PMID 34576298, 2021).
Lynch syndrome (10 papers, 2013 to 2024). An autosomal dominant hereditary neoplastic syndrome characterized by the development of colorectal carcinoma and a high risk of developing endometrial carcinoma, gastric carcinoma, ovarian carcinoma, renal pelvis carcinoma, and small intestinal carcinoma. "We also analyzed a series of 100 patients with Lynch syndrome to evaluate if the EGFR polyA polymorphism could act as a modifier risk factor in patients harboring a MMR gene mutation." (PMID 23565769, 2013). "Recent studies have shown that virtually all (99%) CRCs developing in Lynch syndrome patients display MSI-H; the most mutated genes exhibiting microsatellite repeats are ACVR2A, TGFBR2, EGFR, BPMR2, E2F4, MSH3, BAX and TCF7L2." (PMID 29652830, 2018). "RAS mutational testing may predict response to anti-epidermal growth factor receptor therapy and microsatellite instability or immunohistochemistry testing for MMR proteins to identify Lynch syndrome." (PMID 38836939, 2024). "The roles of EGFR or COX pathways have been less studied in Lynch syndrome." (PMID 38609520, 2024). "Since biomarker testing was mostly relevant for patients considered for anti-EGFR therapy (KRAS, NRAS) or younger patients (MMR testing for Lynch syndrome or BRAF testing for prognostication), it is possible that more young and fit patients with mCRC were tested." (PMID 37071802, 2023). "However, EGFR and SRC genes were found in the LP, non-P, and non-Lynch syndrome groups, but not in the P group, thus suggesting substantial differences in the protein interaction network." (PMID 35014770, 2022).
myocardial ischemia (10 papers, 2012 to 2025). A disorder of cardiac function caused by insufficient blood flow to the muscle tissue of the heart. "Taken together, these results warrant further testing of EGFR-selective TKIs, such as gefitinib, as therapeutics in mammalian models of myocardial ischemia." (PMID 34404849, 2021). "In an animal model of myocardial ischemia, the expression of EGFR in alveolar macrophages was up-regulated, and contributed to the expression of proinflammatory cytokines (such as TNF, IL-6, IL-1β), chemokines (such CXCL2/MIP-2, MCP-1, and CCL3) and iNOS." (PMID 35095926, 2021). "EGFR is involved in diverse cellular responses that include enhanced proliferation and the suppression of apoptosis, having important effects related to β‐Catenin, which has been shown to help protect against myocardial ischemia–reperfusion injury." (PMID 39764606, 2025). "EGFR inhibitors may thus represent a novel approach to be investigated for the treatment of myocardial ischemia–reperfusion injury." (PMID 34404849, 2021). "In a mice model of myocardial ischemia, the interaction between heparin-binding EGF (HB-EGF) and EGFR transactivation is closely related to the proliferation of cardiac fibroblasts and cardiac remodeling." (PMID 27087279, 2016). "On the other hand, two of the upstream targets, epidermal growth factor receptor (EGFR) and ACE, have also been proposed as potential targets for myocardial ischemia." (PMID 23028693, 2012). "While the previous preclinical studies have frequently tested the effects of EGFR inhibition by the TKIs such as erlotinib or AG1478, to our knowledge gefitinib has not been been tested for the treatment of myocardial ischemia." (PMID 34404849, 2021).
neuroendocrine tumors (10 papers, 2010 to 2025). "Another study demonstrated that inhibition of IMP3 expression in cell lines of neuroendocrine tumors leads to downregulation of EGFR and Ki-67, proteins associated with cell proliferation, and these authors suggest IMP3 as a promising therapeutic target." (PMID 36740684, 2023). "Our case demonstrates that transformation into a neuroendocrine tumor is one of the mechanisms of acquired resistance to Almonertinib, and that the retention of EGFR mutations may also occur in LCNEC." (PMID 40040728, 2025). "EGFR is a key driver of tumor growth in certain types of cancers, such as lung cancer and glioblastoma, and is also present in neuroendocrine tumors, exhibiting distinct expression patterns in GEP-NETs and lung NETs." (PMID 38539512, 2024). "The patient was treated with platinum-based chemotherapy followed by EGFR-TKIs due to the elevation of neuroendocrine tumor makers." (PMID 39456595, 2024). "EGFR-mutant NSCLC transforming to neuroendocrine tumors after TKI treatment are usually treated with platinum etoposide, a regiment that yields a clinical response rate of 54% in a retrospective series." (PMID 38203395, 2023). "With the repeat biopsy suggesting LCNEC, we can ascertain that the resistance mechanism was transformation into a neuroendocrine tumor rather than secondary EGFR mutations or bypass activation." (PMID 40040728, 2025).
oropharyngeal squamous cell carcinoma (10 papers, 2006 to 2025). "EGFR expression can be used to predict survival and is associated with smoking status in patients with oropharyngeal squamous cell carcinoma." (PMID 30630536, 2019). "Panitunumab‐IRDye800CW can detect oropharyngeal squamous cell carcinoma even when EGFR expression is low." (PMID 39629534, 2025). "In oropharyngeal squamous cell carcinoma, β-catenin is driven to nuclear translation through E6 oncoprotein by activating epidermal growth factor receptors (EGFR)." (PMID 33469547, 2020). "This study aims to investigate EGFR as a prognostic biomarker in oropharyngeal squamous cell carcinoma (OPSCC)." (PMID 30630536, 2019). "The present study showed that silencing EGFR increased radiosensitivity of both radiosensitive and radioresistant oropharyngeal squamous cell carcinoma (OSCC) cells by inhibiting ER stress signaling (PERK‐eIF2α‐GRP94 and IRE1α‐XBP1‐GRP78)." (PMID 30414263, 2018). "Another report showed that inhibition of the PERK–eIF2α-GRP94 signaling pathway silenced the epidermal growth factor receptor (EGFR) and then increased the radiosensitivity of both radiosensitive and radioresistant oropharyngeal squamous cell carcinoma (OSCC) cells." (PMID 33937330, 2021).
Peritoneal Fibrosis (10 papers, 2017 to 2025). Disorder characterized by a wide range of structural changes in PERITONEUM, resulting from fibrogenic or inflammatory processes. "In the current study, we demonstrate that inhibition of PRMT1 alleviates peritoneal fibrosis by inhibiting the demethylation of H4R3 thereby suppressing the activation of EGFR and downstream signaling pathways." (PMID 40612681, 2025). "Recent studies have found that gefitinib, an inhibitor of EGF receptor (EGFR), can significantly improve peritoneal fibrosis in experimental mouse models by inhibiting STAT3 phosphorylation." (PMID 38780509, 2024). "Our previous studies have demonstrated that epidermal growth factor receptor (EGFR) promotes the development and progression of peritoneal fibrosis via the activation of multiple pro-fibrosis signaling pathways, inflammatory responses and angiogenesis." (PMID 36911746, 2023). "Our previous studies have demonstrated that activated EGFR promotes peritoneal fibrosis by regulating EMT, inflammation, and angiogenesis." (PMID 36911746, 2023). "Studies from our group have demonstrated that the activation of EGFR/ERK/1/2/STAT3 signaling pathway is related to the progression of peritoneal fibrosis." (PMID 36911746, 2023). "To elucidate the role of P-EGFR in peritoneal fibrosis, we tested the expression of p-EGFR by immunoblot analysis and immunohistochemical staining." (PMID 31727005, 2019). "Although the role and mechanisms of these RTKs in peritoneal fibrosis remains poorly understood, our recent studies have shown that EGFR is critically involved in the progression of peritoneal fibrosis." (PMID 29137389, 2017). "Our recent studies have shown that EGFR activation is critically involved in the development and progression of peritoneal fibrosis." (PMID 29137389, 2017). "Our recent studies have demonstrated that EGFR is a critical mediator of renal and peritoneal fibrosis." (PMID 29179471, 2017). "Studies from our group and others have demonstrated that activation of the EGFR/STAT3 pathway is involved in the progression of peritoneal fibrosis." (PMID 29179471, 2017). "Moreover, pharmacological inhibition of EGFR attenuates development and progression of peritoneal fibrosis in animal models of peritoneal fibrosis induced by chlorhexidine gluconate (CG) or peritoneal dialysates with high glucose." (PMID 31727005, 2019). "Since our recent studies have demonstrated that EGFR activation is critically involved in the development of peritoneal fibrosis, there is the possibility that Src may induce peritoneal fibrosis through activation of EGFR." (PMID 29137389, 2017). "Furthermore, suramin may reduce peritoneal fibrosis through a mechanism involved in the suppression of EGFR activation." (PMID 31727005, 2019). "HDAC6 inhibition may also attenuate peritoneal fibrosis via the targeting of EGFR signaling." (PMID 29179471, 2017). "In conclusion, DOT1L promotes the expression and activation of tyrosine kinases, specifically EGFR in mesothelial cells and JAK3 in macrophages, driving cell differentiation towards a pro-fibrotic phenotype, ultimately leading to peritoneal fibrosis." (PMID 39749340, 2024). "In summary, DOT1L promoted the expression and activation of tyrosine kinases (EGFR in mesothelial cells and JAK3 in macrophages), promoting cells differentiate into profibrotic phenotype and thus peritoneal fibrosis." (PMID 38172378, 2024). "We demonstrated that HDAC8 promoted the EMT of HPMCs via EGFR/ERK1/2/STAT3/HIF-1α, induced M2 macrophage polarization via STAT6 and PI3K/Akt signaling pathways, and ultimately accelerated the process of peritoneal fibrosis." (PMID 36911746, 2023). "Like nintedanib, treatment with gefitinib, a potent EGFR inhibitor, also attenuates MMT and peritoneal fibrosis." (PMID 33949772, 2021). "Inhibition of autophagy with 3-MA prevents peritoneal fibrosis by regulating TGF-β/Smad3, EGFR/ERK1/2, STAT3/NF-κB and β-Catenin axis both in vivo and in vitro systems." (PMID 34497522, 2021).
Peritoneal Fibrosis (continued). "Our results indicated that suramin can attenuate progression of peritoneal fibrosis by a mechanism involving inhibition of the TGF-β1/Smad3 and EGFR signaling pathways as well as suppression of multiple proinflammatory cytokines." (PMID 31727005, 2019). "DOT1L proceeds mesenchymal phenotype differentiation of MCs through upregulating and activating EGFR, and facilitates M2 differentiation of macrophages by upregulating and activating JAK3, subsequently promoting the deposition of ECM and subsequent peritoneal fibrosis." (PMID 38172378, 2024). "Moreover, inhibition therapy targeting EZH2 in both models alleviated peritoneal fibrosis and suppressed the activation of various pro-fibrotic signaling pathways, such as TGF-β1/Smad3, Notch1, EGFR, and Src, as well as phosphorylation events involving STAT3 and NF-κB." (PMID 39749340, 2024). "The phosphorylation of EGFR subsequently leads to the activation of several intracellular signaling pathways, including extracellular signal-regulated kinases 1/2 (ERK 1/2) and signal transducer and activator of transcription 3 (STAT3) during peritoneal fibrosis." (PMID 36911746, 2023). "Therefore, we believe that PRMT1 promotes peritoneal fibrosis through the regulation of EGFR, but EGFR may not be its only substrate protein during the process of peritoneal fibrosis." (PMID 40612681, 2025).